MUC16 (mucin 16, cell surface associated)
Diseases named in the same sentence as MUC16 in open-access papers (continued):
Sharing a sentence is not in itself a finding about the gene and the disease.
cancer (continued). "First, multiple genes already used in the clinic as cancer biomarkers encode proteins within the Src signature, including Her2, MUC16, PLAU, SERPINE1, Aurora A kinase, Cyclin B1, GRB7 and Ki-67." (PMID 29904729, 2018). "MUC16 which was found to have an impact on the cancer immunogenicity and has been shown to be implicated in the inactivation of NK cells and monocytes was found mutated." (PMID 30459932, 2018). "For example, MUC16 was found mutated in 7.4% of cancers (2225 mutated out of 30047 tested samples), MLL2 in 4.8% (1633 out of 34019), FAT1 in 3.81% (1169 out of 30688) and BAI3 in 2.75% (823 out of 30208)." (PMID 30459932, 2018). "It has been demonstrated that mucins such as MUC4 and MUC13 are associated with cancer development; the circulating level of MUC16 is even used to monitor patients with ovarian cancer." (PMID 29062084, 2017). "MUC16 (mucin 16) is a 132 kb gene encoding the mucin protein, a glycoprotein associated with cancers, whereas SSPO (subcommissural organ spondin) is a 58 kb gene that encodes a protein involved in the modulation of neuronal aggregation." (PMID 29181379, 2017). "The array staining generally revealed that strong cytokine expression was associated with elevated MUC16 expression in many cancers." (PMID 26918940, 2016). "According to the authors, large proteins (>4000 amino acids) are found to be mutated at a significant frequency, thus making some of them falsely associated with various cancers, e.g., MUC16 and PCLO in DLBCL." (PMID 27164089, 2016). "Cancer-associated mucin MUC16 is over expressed in PDAC and its expression increases in tandem with PDAC progression." (PMID 27382435, 2016). "On the DNA level, MUC16 is frequently mutated in many cancer types, though more likely due to its very large gene size." (PMID 26555578, 2015). "Recent studies show that in addition to OC, MUC16 is expressed in multiple cancer types and is associated with poor prognosis." (PMID 25691062, 2015). "In particular, over-expression of the aberrantly glycosylated membrane bound mucins MUC1 and MUC16 is associated with several types of cancer." (PMID 24039759, 2013). "Previous work using this method showed that the mucins MUC1, MUC5AC, and MUC16 are major cancer-associated carriers of the CA 19-9 antigen in the blood." (PMID 22220206, 2011). "The detection of MUC16 in high-grade PanINs (considered to be the true dysplastic lesions with a high risk for invasive cancer) suggests its potential use in the early detection of potentially malignant lesions in the pancreas." (PMID 22066010, 2011). "MUC16 has been implicated in modulating cell adhesion, immune evasion, and chemoresistance in other cancers, while CMYA5 is involved in cytoskeletal organization and could affect cell motility." (PMID 41037214, 2025). "Another mutated gene is MUC16, mucin 16, also known as a cancer antibody 125 (CA125)." (PMID 39493752, 2024). "Mucin-16 (MUC16) has been linked to glycolysis and immune response in different cancers." (PMID 39219440, 2024). "MUC16 mutations were also identified in the initial clone of 2 cancers." (PMID 38175731, 2024). "The abnormal expression of MUC16 is remarkably associated with the poor prognosis of many cancers." (PMID 37814942, 2023).
cancer (continued). "LC is a major contributor to cancer-associated deaths worldwide, and LC with MUC16 mutation causes higher mutational burden, elevated immune checkpoint protein expression, enhanced PD-L1 amplification, and increased T-cell infiltration, all of which can be regulated with the use of PD-1 inhibitors." (PMID 37341998, 2023). "In the pan-cancer dataset, MUC16 and TTN mutations each showed significantly better OS30." (PMID 36127384, 2022). "Furthermore, MUC16 mutations have been implicated as cancer-driving in a pan-cancer analysis that assessed the functional impact of mutations on differential gene expression profiles." (PMID 33946379, 2021). "Although, Msln-/- and Muc16-/- mice have a normal phenotype until injury or stress, when subjected to experimental model of liver cancer, Msln-knockout mice developed a defect in activation of cancer associated myofibroblasts." (PMID 34966784, 2021). "In addition, studies have reported that in the pan-cancer immunotherapy dataset, MUC16 and TTN mutations were associated with higher TMB and better OS." (PMID 34249711, 2021). "In infected cells, the S2-subunit post-transcriptionally promotes MUC16, a large transmembrane mucin that seems to have evolved to monitor and repair damaged epithelia, but these functions can be hijacked by pathogenic microbiota, viruses or cancer cells." (PMID 34659373, 2021). "The MUC16 gene is among the three most frequently mutated genes in multiple cancer types." (PMID 33322519, 2020). "As the third most frequently mutated gene in cancers, the association between MUC16 mutation and response to immune checkpoint inhibitors (ICIs) in solid tumors remains unclear." (PMID 32845327, 2020). "MUC16 was one of three genes having the highest mutation frequency across multiple cancer types." (PMID 29552305, 2018). "Furthermore, we showed that elevated MUC16 expression is associated with elevated cytokine levels in several cancers of female reproductive tissues." (PMID 26918940, 2016). "Further, MUC16 knockdown studies in breast, ovarian and PC cells associated it in imparting protumorigenic, prometaststic, chemo resistant and anti-apoptotic properties to cancer cells." (PMID 25691062, 2015). "The other frequently mutated genes, such as SYNE1, MUC16, etc. have been found to be mutated in other cancer types and may be novel candidate driver mutations in early stage of CRC tumorigenesis." (PMID 25923178, 2015). "We found that the mucins MUC1, MUC5AC, and MUC16 are indeed major cancer-associated carriers of CA 19-9, but because of the diversity among patients in the proteins that carry CA 19-9, the detection of CA 19-9 on any single protein did not out-perform total CA 19-9." (PMID 22220206, 2011). "However, due to the fact that MUC16 consists of ~ 22,000 amino acids, the variant frequency corrected by sequence length and mutational heterogeneity resulted in exclusion of MUC16 as one of the most altered genes in most cancer types, including BC." (PMID 31254045, 2020). "Furthermore, we augment that a careful mapping of MUC16 and other cancer‐associated glycoproteins may provide the necessary structural information for highly specific biomarkers and targeted therapeutics." (PMID 28156048, 2017). "In summary, this study extensively investigated missense nsSNPs in the MUC16 gene, prevalent in various cancers." (PMID 40478193, 2025). "This ADC aims to exploit the overexpression of MUC16 in certain cancers by delivering MMAF directly into cancer cells through receptor-mediated endocytosis, disrupting microtubule dynamics and inducing cell death." (PMID 41347223, 2025). "Its interaction with the CA125/MUC16 ovarian cancer antigen mediates cell adhesion and has been shown to play a role in metastasis of ovarian cancers." (PMID 40568084, 2025).
cancer (continued). "The CA‐125 peptide epitope of mucin MUC16 is known to bind to mesothelin with high affinity, promoting the attachment of cancer cells to the mesothelial lining and leading to peritoneal metastasis." (PMID 40067023, 2025). "The increased abundance of MUC16 in the disease group is also noteworthy, as this aberrant glycoprotein is highly expressed in several solid tumors and different types of cancers." (PMID 40457720, 2025). "In murine models, MUC16 inhibits the cytolytic functions of natural killer (NK) cells and macrophages, mimicking its effects on human immune cells and enabling cancer cells to evade innate immune surveillance." (PMID 40655139, 2025). "Despite these limitations, our investigational findings shed light on MUC16‐related cancers, paving the way for future research and potential therapeutic avenues." (PMID 40478193, 2025). "In the last half-decade, MUC16 has been used for the biomarker-based detection of cancer using tools like fluorescence-guided surgery (FGS) and positron emission tomography (PET) imaging." (PMID 40149293, 2025). "MUC4, MUC1, and MUC16 are involved in the regional invasion and migration of cancer cells through various signaling pathways." (PMID 40699805, 2025). "The cancer-associated transcripts including NF1, ATM, MUC16, and KMT2C, were found at higher mRNA levels with ExCy." (PMID 40598203, 2025). "The MUC16-targeted conjugate facilitates cancer detection in early- and late-stage disease models over 24 h post-administration and does not induce toxicity even after 96 h in the circulation." (PMID 40149293, 2025). "Mesothelin is overexpressed in many cancers and interacts with carbohydrate antigen‐125 (CA‐125, also known as mucin‐16 or MUC16)." (PMID 40923371, 2025). "When cells lose their polarity and become cancerous, MUC16 is overexpressed and releases more of the extracellular domain, i.e., CA-125, into the serum, therefore contributing to cancer development." (PMID 40385462, 2025). "The current chapter shows the importance of various mucins (MUC1, MUC3A, MUC4, MUC4β, MUC5AC, MUC5B, MUC7, and MUC16) and their mucin-bound carrier proteins in different cancers." (PMID 40699805, 2025). "MSLN networks with a cancer antigen CA125/MUC16 trigger a chain of signaling events, which in turn suppresses a Dickkopf-1 (DKK1), a secreted protein that inhibits the Wnt signaling pathway and stimulates cell migration." (PMID 40227616, 2025). "Overexpression of MUC16 contributes to the differentiation, proliferation, invasion and metastasis of cancer cells in ovarian, endometrial, pancreatic, colon, breast and non‐small‐cell lung cancers." (PMID 40478193, 2025). "Cluster analysis identified a pro-cancer role for the ERS high-risk subgroup, which had lower mutation rates of key genes (SPOP and MUC16), multiple low-expressed immune-related molecules, and differential expression in macrophages (M1 and M2)." (PMID 38643190, 2024). "In fact, MUC16 is a protein that has shown promise as a novel biomarker in cancer, particularly in the context of ovarian cancer." (PMID 38956143, 2024). "All of these results suggested that MUC16 shows potential as a marker for the malignant phenotypic transformation of malignant tumors." (PMID 39127853, 2024). "According to the list of the top 10 most frequently mutated genes, MUC4, MUC16, KMT2C, and PREX2 were annotated as cancer driver genes." (PMID 39338204, 2024). "All patients carried at least three mutated cancer genes, except for case 11 with only a FAM135B and case 15 with MUC16 and PRSS1 gene mutations." (PMID 38807144, 2024). "This review examines the roles of MUC1 and MUC16 in cancer immune regulation and therapeutic effectiveness, exploring their potential in precision medicine." (PMID 38361923, 2024).
cancer (continued). "We next investigated our scFv binding to MUC16-overexpressing cancer cells through fixed or live cell imaging analysis and also evaluated if internalization took place." (PMID 38374055, 2024). "The aberrant expression of MUC16 (CA125) is often implicated in various diseases, and there has been growing interest in the development of targeting drugs for treating cancer cells which overexpress MUC16." (PMID 38637885, 2024). "Parallel to MUC1, the modulation of MUC16 expression has emerged as a key factor in augmenting the response of cancer cells to therapeutic interventions." (PMID 38361923, 2024). "Recent clinical trials have highlighted MUC1 and MUC16’s significant potential as immunotherapy targets in advanced cancer treatment, particularly in various solid tumors." (PMID 38361923, 2024). "The MUC16 tandem repeat domain and C-terminus in three human cancer cell lines (OVCAR3, OVCAR5, and Kuramochi) and three patient-derived tumors were sequenced on an Oxford Nanopore platform." (PMID 38197671, 2024). "MUC16, of which the biomarker CA-125 is a fragment, plays a significant role in cancer progression by stimulating cell division and regulating key signaling pathways." (PMID 39685591, 2024). "Genes PTEN, CSMD3, and MUC16 also occur in more than half the cancer types, suggesting their relevance as general cancer driver genes that impact multiple cancer types." (PMID 39040139, 2024). "MUC16 stimulates cell adhesion, growth, and metastasis, and evading attacks from natural killer cells aiding cancer cell progression." (PMID 39149564, 2024). "Elevated MUC16 expression is correlated with cancer progression, metastasis, and poor prognosis in patients." (PMID 39493752, 2024). "By binding both cancer and host immune T cells, it bridges and facilitates T cell recognition and elimination of MUC16-expressing cancer cells." (PMID 39534871, 2024). "All the data were obtained from the cancer genome atlas database to assess the prognostic value and potential mechanism of MUC16 in LUAD." (PMID 37932988, 2023). "It is evident from the volcano plot that highly mutated genes MUC4, MUC16, CIITA, and ALK are mutated and overexpressed, of which ALK and CIITA are cancer census genes, whereas NCOR2 a transcriptional corepressor was mutated and downregulated." (PMID 37091785, 2023). "The maximum inhibition was observed at 25 and 50 μg/ml in most cancer lines, and the differential response among the cell lines indicated varying expression of MUC16 in different cancer cell lines." (PMID 37567918, 2023). "Previous studies demonstrated the overexpression of MUC16 and its impact on migration and invasion of cancer cells." (PMID 36918912, 2023). "The variable effects of mAb on the the growth and proliferation of various cancer lines can be explained by the differences in MUC16 expression levels, which were consistent with in vitro binding data of mAb on different cell lines." (PMID 37567918, 2023). "Similar to a previous ST study, we observed the high expression of mucin family genes in cancer cells, such as MUC16, MUC4, and MUC5B." (PMID 37124494, 2023). "Transmembrane mucins (MUC1 and MUC16) support cancer progression by altering homozygous and heterozygous cell-cell adhesion potential." (PMID 36816942, 2023). "MUC16 is a cell surface glycoprotein which can be elevated in tissue and sera of patients with various cancers and is mostly used in the diagnosis and prognostication of ovarian cancer." (PMID 36670203, 2023).
cancer (continued). "Previous studies have demonstrated the association of certain cancer-related genes (e.g., PTPRT, MUC16, KMT2 family, FAT family genes etc.)with the response to ICI therapy." (PMID 37626083, 2023). "Circulating PD-L1, HGF, and MUC-16 have been associated with poor survival in BTC and other cancers, but all previous studies on BTC included less than 250 patients and lacked independent validation cohorts." (PMID 36831406, 2023). "The mutational landscape of our LUAD cohort was very similar to what is expected for this cancer type, with KRAS being the top mutated gene (41%) followed by RYR2 (34%) and MUC16 (32%)." (PMID 37501683, 2023). "In line with the previous studies on the role of MUC16 in cancer cell metastasis, we examined the ability of ch5E6 to impact the invasive and migratory potential of cancer cells in matrigel coated trans well insert and Boyden chamber-based assays." (PMID 37567918, 2023). "Aberrantly expressed MUC16 is found in various cancers, which plays important roles in carcinogenesis, anti-cancer immune response and acquired resistance to drugs." (PMID 37077919, 2023). "A human bispecific antibody (REGN4018) and Meso-TR3 chimera have the potential to kill MUC16-positive cancer cells." (PMID 37682202, 2023). "MUC16 (also known as CA125) is overexpressed in a variety of cancers and plays an important role in tumorigenesis and acquired therapeutic resistance." (PMID 37024829, 2023). "We observed other frequently-mutated genes in AS-HN including CSMD3, MUC16, and LRP1B, which are known cancer-related genes." (PMID 37106027, 2023). "Aberrant MUC16 has been reported to be produced in diverse carcinomas such as ovarian, lung, breast, gastrointestinal, kidney, cervical, uterine, and endometrial." (PMID 37455827, 2023). "In vitro studies indicate that amatuximab inhibits mesothelin interaction with CA125/MUC16 and such a blockage reduces the cancer’s ability to metastasize and invade into other tissues." (PMID 35326701, 2022). "This study is the first report of a fully human monoclonal anti-CA125/MUC16 antibody for PET imaging of CA125/MUC16-expressing cancers with potential for further development as radiopharmaceuticals for targeted therapy." (PMID 36559316, 2022). "Immunoconjugates with high specificity and affinity to MUC16 can deliver a tumoricidal radiation dose to cancer cells." (PMID 36559316, 2022). "Among the biomarker candidates we screened, MUC16 has been proposed to exert roles in the innate defense of tracheal epithelium or the immune microenvironment of cancer." (PMID 35954383, 2022). "This study also found that a lower cut-off value should be adopted for CA125 (MUC16) for the diagnosis of malignant pancreatic IPMNs." (PMID 36155113, 2022). "Together, these results demonstrate the critical role of truncated O-glycans and truncated O-glycan-containing MUC16 in enhancing cancer cell migration." (PMID 35628269, 2022). "MUC16 is an important membrane protein that maintains the normal cellular function and is involved in cancer development." (PMID 36199046, 2022). "Analyzing the three GC cohorts (The Cancer Genome Atlas-Stomach Adenocarcinoma, International Cancer Genome Consortium [ICGC]-China, and ICGC-Japan) revealed that MUC16 was one of the most frequently mutated genes in patients with GC." (PMID 35211490, 2022).